JAK1 (Janus kinase 1)
Diseases named in the same sentence as JAK1 in open-access papers (continued):
Sharing a sentence is not in itself a finding about the gene and the disease.
tumor (continued). "In tumor-associated macrophages, upregulated CD36 increases lipid uptake, enhancing fatty acid oxidation and mitochondrial ROS production, which activates JAK1 phosphorylation, SHP1 dephosphorylation, and STAT signaling, promoting pro-tumor TAM polarization." (PMID 41474538, 2025). "In our current study, we gathered clinical samples of ATC, PTC, and NT tissues and established a noteworthy confirmation of the heightened expression levels of JAK1, p-JAK1, JAK2, p-JAK2, STAT3, and p-STAT3 proteins within the tumor cells of ATC patients." (PMID 38336839, 2024). "We observed significant overexpression of JAK1 and STAT3 in tumor cells, which are pivotal members of the JAK/STAT pathway." (PMID 38191424, 2024). "The deactivation of JAK1 and JAK2 signaling resulted in the development of IFN-γ resistance, compromising immune surveillance and promoting tumor cell growth." (PMID 38785789, 2024). "METTL3 enhances ribosomal translation efficiency through the METTL3/m6A/JAK1/STAT3 axis and facilitates tumor immune evasion." (PMID 38879589, 2024). "The results showed that Ruxo significantly inhibited the JAK1/2-STAT3 pathway and exhibited remarkable anti-tumor activity in ATC cells." (PMID 38336839, 2024). "Surprisingly, it appears that the analysis of JAK1/2-STAT3, along with their phosphorylated forms, within ATC patient tumor tissues has been relatively infrequent." (PMID 38336839, 2024). "Guide RNAs were employed to delete B2m, Jak1, or Psmb9 genes in ICB-responsive EMT6 murine tumor cells." (PMID 38427670, 2024). "In conjunction with YTH N6-methyladenosine RNA Binding Protein 1 (YTHDF1), METTL3 mediates m6A modification on JAK1 mRNA, enhancing JAK1 and STAT3 expression and promoting tumor immune escape." (PMID 39659524, 2024). "Additionally, in vivo experiments demonstrated that treatment with an IL-6 antibody decreases PD-L1 expression in tumor regions by modulating its glycosylation while enhancing JAK1/nonglycosylated PD-L1 association, JAK1-driven Tyr phosphorylation, and STAT3 recruitment." (PMID 39690423, 2024). "Through MHC recognition, CD8+T cells activate the JAK1/STAT1 pathway in tumor cells, impairing the function of System Xc and reducing GSH and GPX4 expression to promote tumor cell ferroptosis." (PMID 38853203, 2024). "In the XLLXF combined with trastuzumab groups, we observed increased expressions of JAK1 and TNF-α on lymphocytes in tumor tissues by IHC staining." (PMID 38379418, 2024). "YTHDF1 recognizes m6A modification of JAK1 mRNA in Tumor-infiltrating myeloid cells mediated by METTL3, and METTL3-m6A-YTHDF1 enhances the translation of JAK1 mRNA, subsequently promoting STAT3 phosphorylation and tumor growth in mice." (PMID 39726589, 2024). "E3 ubiquitin ligase VHL can induce the activation of the JAK1/STAT1 pathway by degrading PTP1B and TC-PTP, thus promoting the expression of MCH I in tumor cells." (PMID 39253578, 2024). "Knockdown of IL20RA in CRC cell lines downregulates Janus kinase 1 (JAK1) and signal transducer and activator of transcription 3 (STAT3) and consistently suppress tumor growth." (PMID 39664380, 2024). "The heterodimeric IFNGR1/IFNGR2 receptor complex on tumor cells binds to IFN-γ released by tumor-specific T lymphocytes, activating JAK1 and JAK2, which subsequently phosphorylate a transcription factor known as STAT1." (PMID 38785789, 2024). "JAK1/JAK2 inhibitor (JAKi) has been applied to inhibit expression of TCIR ligands and improved ICBT response in preclinical tumour models." (PMID 37503572, 2023). "The deleted regions contained the tumour suppressors CDKN2C, SDHB, and SFPQ in 1p and CDKN2A in 9p in metastatic samples and the tumour suppressors BCL10 and NOTCH2 and the oncogenes JAK1 and NRAS in 1p in the non‐metastatic sample group." (PMID 37622176, 2023). "Co-treating patient and transgenic mouse lung-tissue-derived tumour organoids with AICAR and JAK1 and EGFR inhibitors reduced their growth." (PMID 36810913, 2023).
tumor (continued). "Confirming screen robustness, sgRNAs targeting genes required for T cell function were depleted from the tumor, including Tap1, B2m, CD47, Jak1, and Jak3." (PMID 38099496, 2023). "EHBP1L1 interacts with and stabilizes Janus kinase 1 (JAK1), thus significantly inhibiting tumor growth and enhancing anti‐tumor immune response." (PMID 36775874, 2023). "Meanwhile, in tumor-infiltrating myeloid cells (TIMs), METTL3 mediates the m6A modification of JAK1 RNA and enhances the translation efficiency of the JAK1 protein, followed by the activation of STAT3 phosphorylation to promote tumor cell growth." (PMID 37996892, 2023). "Inhibition of the JAK/STAT pathway by ruxolitinib, a JAK1/JAK2 inhibitor, showed promising anti-tumor activity in patients with advanced T cell malignancies, especially tumors with JAK/STAT pathway aberrations." (PMID 37077916, 2023). "JAK1 overexpression restored PD‐L1 expression in EHBP1L1 knockdown cells, and promoted tumor growth in BALB/c mice." (PMID 36775874, 2023). "Together with the impact on IL4-signalling via the JAK1/STAT6 axis, our data strongly support an early tumor suppressive role of miR-494-5p in CRC." (PMID 38201452, 2023). "IL-20 subfamily cytokines have been shown to activate the JAK1/STAT3 signaling pathway, which plays a crucial role in cancer cell proliferation and tumor progression." (PMID 36006737, 2022). "In the present study, to verify that AZD3759 exerted anti-tumor properties not only by inhibiting EGFR signaling, but also by suppressing JAK1 signaling, we established JAK1-overexpressed PC-9 cells." (PMID 34738874, 2022). "In line with the fact that Ruxo is a well-established JAK1/2 inhibitor, we observed the expected suppression of p-JAK2 and p-STAT3 in tumor (CD45−) cells by Ruxo." (PMID 36008408, 2022). "Among all JAK1/STAT pathways, the JAK1/STAT3 pathway is reported to play an important role in the proliferation, apoptosis, migration, and invasion of tumor cells." (PMID 34738874, 2022). "Collectively, we define a critical role of LXN/JAK1/STAT3 signal in macrophage and highlights the potential role of LXN in tumor immune-escape by regulating macrophage polarization, as well as the expression of immune checkpoint PD-L2." (PMID 36323670, 2022). "To directly confirm this finding, we analyzed phosphorylation of JAK1 and JAK2 (p-JAK1 and p-JAK2) by Western blot (WB) in cells cultured under normoxia (21% O2) and hypoxia (1% O2, mimicking hypoxic tumor microenvironment [TME])." (PMID 36008408, 2022). "It has been proposed that the JAK/STAT signaling pathway is involved in the development of UCEC, and targeted inhibition of the IL‐6 receptor and its downstream effectors JAK1 and STAT3 significantly reduces UCEC tumor cell growth." (PMID 35244291, 2022). "LIF is aberrantly secreted by tumour cells and promotes tumour progression in pancreatic and other solid tumours through aberrant activation of the LIF receptor (LIFR) and downstream signalling that involves the JAK1/STAT3 pathway." (PMID 36359879, 2022). "The combination of osimertinib and JAK1 inhibitor (AZD4205) had synergistic activity compared to each agent alone in PC-9 and HCC827 models, with an observed increased degree of tumor regression, delayed tumor regrowth, and evidence of knockdown of pSTAT3." (PMID 34773474, 2022). "This is in line with previous reports showing that downmodulation of JAK1 and JAK2, both essential tyrosine kinases in the IFNγ-signaling pathway, in tumor cells results in resistance to CD3 bsAbs." (PMID 36271507, 2022). "To examine the significance of upstream genes involved in STAT3 activation regulating properties of tumor spheroids, we knocked down FN1, ITGA5, JAK1, JAK2, LDB1, and LMO2 from the cells." (PMID 36359204, 2022). "Mechanistically, tumor cells induced osteoclasts to secrete the IL-20RB ligand IL-19, and IL-19 stimulated IL-20RB–expressing tumor cells to activate downstream JAK1/STAT3 signaling, leading to enhanced proliferation of tumor cells in bone." (PMID 36006737, 2022).
tumor (continued). "We found that only five genes (MITF, CCR7, JAK1, ELN, and SLC6A4) functioned as tumor suppressors, whereas the remaining 17 genes functioned as oncogenes." (PMID 36425071, 2022). "For example, parallel comparisons of apoptosis and DNA damage in RA-treated JAK1 overexpressed PC-9 cells incubated with AZD3759 and osimertinib will be conducted, as well as a parallel comparison of their anti-tumor efficacies in vivo." (PMID 34738874, 2022). "As shown in the volcano plot, SU decreased GZMB expression and upregulated genes related to inflammatory activation (FOS, JUN, NFKBIA, DUSP2, JAK1, PIM1), tumor immunity (CD47, PCBP2, EIF5A, PDIA3, EGR1), and DNA damage (H2AFX, DDIT3, GADD45B)." (PMID 34824394, 2021). "We observed a substantial reduction in the phosphorylation of STAT3, JAK1, and JAK2 in the tumor tissues of mice treated with 100 mg/kg of Tris DBA." (PMID 34771643, 2021). "Ruxolitinib, a JAK1/2 inhibitor, in combination with the HDAC inhibitor resminostat, showed substantial anti-tumor effects in two CTCL cell lines in vitro." (PMID 34681738, 2021). "We further analyzed the phosphorylation status of STAT3, JAK1, and JAK2 proteins in the tumor tissues of the xenograft MM mouse model." (PMID 34771643, 2021). "A previous study illustrated that the crosstalk between JAK1/STAT3 and NF‐kB is central for tumor progression." (PMID 33634982, 2021). "On day 7 after tumor challenge, a 3-fold increase in the frequency of H-2Kb/SIY+ CD8+ tumor infiltrating lymphocytes (TILs) was observed in IFNγR2- and Jak1-mutant tumors compared to WT tumors." (PMID 32001684, 2020). "As with the generation of IFNγR2- and Jak1-mutant B16.SIY tumor cells, we generated MC38 IFNγR2- and Jak1-mutant tumors by establishing a founder cell line and a similar single-cell CRISPR/Cas9 mutagenesis method." (PMID 32001684, 2020). "To this end, we first investigated both IL10RA and IL10RB and its downstream targets JAK1 and TYK2 gene expression levels in 370 HCC tumor samples using the publicly available The Cancer Genome Atlas (TCGA) dataset." (PMID 32443546, 2020). "TB11-Fhit-transfected tumor cells showed a significant increase in the expression of IRF-1, Jak1, Ptpsh1, Stat1, Stat2, and Stat3 genes." (PMID 32545680, 2020). "Inhibited JAK1,2/STAT3 signalling pathway activation was also confirmed in EGFR-TKI-treated NSCLC tumour tissues." (PMID 31892990, 2020). "Pharmacological inhibition with both 5-azacytidine and ruxolitinib results in the long-term abrogation of JAK1/STAT3 phosphorylation and rescues the expression of SHP-1, thereby inhibiting the tumor-promoting invasive phenotype of CAFs." (PMID 32546182, 2020). "To be able to examine the role of tumor-intrinsic IFN-γ signaling in the antitumor immune response in vivo, we generated IFNγR2- and Jak1-mutant B16.SIY tumor cell lines by single-cell cloning using the sgRNAs identified from the CRISPR/Cas9 screen." (PMID 32001684, 2020). "In order to assess the behavior of IFNγR2- and Jak1-mutant tumor cells in vivo, we subcutaneously implanted mutant or WT tumor cells into C57BL/6 mice and tracked tumor growth." (PMID 32001684, 2020). "JAK1 levels were correlated with the T cell transcript-enriched LYM metagene signature and was significantly lower in the low tumor infiltrating lymphocytes (TILs) group." (PMID 31790361, 2019). "The results showed that there was a significant correlation between JAK1 mRNA levels and the LYM metagene in tumor samples from TCGA." (PMID 31790361, 2019). "Notably, JAK1/2 inhibition led to the establishment of an antitumorigenic tumor microenvironment, characterized by decreased levels of tumor‐promoting chemokines and cytokines and reduced numbers of infiltrating myeloid derived suppressor cells, thereby impairing tumor growth." (PMID 31407334, 2019).
tumor (continued). "Although the cellular mechanisms have not been fully elucidated, truncating somatic JAK1 mutations in gynecological carcinomas reduced IFNγ-induced MHC class I expression at the tumor cell surface, which could reduce immune recognition and facilitate immune evasion." (PMID 31552026, 2019). "Based on the availability of autologous tumor specimens, we focused on NUP214 neoepitope-specific CD4+ T-cells obtained from TILs of Pt #19 and JAK1 neoepitope-specific CD4+ T-cells obtained from TILs of Pt #11." (PMID 31221207, 2019). "We also observed that OP-D was effective in suppressing the expression of STAT3, JAK1, JAK2, and Src phosphorylation in tumor tissues." (PMID 30413072, 2018). "Additive or synergistic inhibition of tumor growth was observed when INCB053914 was combined with selective PI3Kδ inhibition, selective JAK1 or JAK1/2 inhibition, or cytarabine." (PMID 29927999, 2018). "To overcome resistance of B16 Jak1-KO tumor cells to pmel ACT, we tested intratumoral delivery of BO-112, which has direct anti-tumor efficacy against B16 and augments anti-tumor efficacy of pmel ACT against B16." (PMID 30400822, 2018). "Since Janus kinases (JAKs) mediate STAT3 activation in tumor angiogenesis, we first tested the effect of VEGFA on Jak1 and Jak2 tyrosine phosphorylation in HRMVECs." (PMID 27210483, 2016). "In addition, JAK1 mutations may have a negative effect on tumor immune surveillance due to lack of HLA class I upregulation on the cell surface." (PMID 27213585, 2016). "In summary, IL10 triggers positive feedback between JAK1 and Src to amplify the activity of STAT3, thus leading to tumor formation." (PMID 26956044, 2016). "JAK1 and STAT3 mutants result in a hyperactivated STAT3, which sustains cell transformation, and whose pharmacological ablation produces tumor cell growth inhibition." (PMID 26501073, 2015). "The results showed that treatment with combination of BSN and paclitaxel strongly inhibited constitutive p-JAK1, p-JAK2, and p-Src in NSCLC tumor tissues." (PMID 25788267, 2015). "AZD1480 is a potent, competitive small-molecule inhibitor of JAK1/2 kinases, that is capable of blocking STAT3 phosphorylation and inhibiting tumor growth in a STAT3-dependent manner." (PMID 25149535, 2014). "Moreover, JAK1-inhibitors may reduce anti-tumor immune responses elicited by oncolytic virotherapy." (PMID 28548066, 2014). "A number of tumor cell survival proteins, such as phospho-STAT3 Tyr705, phospho-Erk and total Jak1 were up-regulated in A2780 cells after exposure to γδ T cells." (PMID 21935360, 2011). "Silencing JAK1, JAK2 or TYK2 using RNA interference (RNAi) inhibits FGF2-mediated proliferation and results in the sensitization of tumor cells to chemotherapy-induced killing." (PMID 21625473, 2011). "For example, tumor cell lines with defects in STAT1, IRF9 and Jak1 have been identified and have been found to have reduced in vitro responsiveness to IFN-α." (PMID 20398276, 2010). "Immunohistochemistry using IL-6R, JAK1, STAT3, pSTAT3Tyr705 and pSTAT3Ser727 antibodies was performed on 50 matched hormone-sensitive and hormone-refractory tumours pairs." (PMID 17595657, 2007). "Furthermore, we found that the levels of IL6, as well as the phosphorylation of JAK1 and ACAP4 at Tyr843, were significantly greater in tumor tissues from HCC patients than in adjacent tissues." (PMID 39744421, 2025). "ERβ activation in macrophages has been shown to inhibit tumor growth in certain cancers by suppressing the JAK1/STAT6 pathway, which may contribute to a less immunosuppressive tumor microenvironment." (PMID 40438106, 2025). "JAK1, a member of the JAK kinase family, is involved in the signal transduction of multiple cytokine pathways and is crucial in the onset and progression of inflammation and tumours." (PMID 40746612, 2025).
tumor (continued). "Overall, while STAT3 inhibition did not significantly impact cell viability, proliferation, or CD44 induction after HER2 inhibition, JAK1 inhibition appeared to sensitize cells to HER2 inhibition and impair proliferation during the recovery phase in CD24+/CD44+ tumor cells." (PMID 40430044, 2025). "Furthermore, acetate engaged G protein-coupled receptor 43 (GPR43) on hepatocytes, inhibiting the IL-6/JAK1/STAT3 pathway, inducing apoptosis of NAFLD/HCC tumor cells, preventing tumor formation, and enhancing intestinal barrier function." (PMID 40165786, 2025). "Targeted knockout of DMT1 inhibits iron uptake by colon epithelial cells, disrupts the iron-regulated signaling pathway mediated by CDK1, JAK1 and STAT3, and consequently suppresses tumor cell proliferation in colon cancer mouse models, thereby reducing tumor burden." (PMID 40144390, 2025). "Pharmacologic inhibition of JAK1/2 with ruxolitinib improved body weight, fat mass, and overall survival without altering tumor burden." (PMID 41278737, 2025). "More critically, this paper, for the initial time, elaborates that IFN-γ modulates the expression of ANGPT2 and Tie2 via the AKT-FOXO1 and JAK1/2-STAT1 pathways, thereby providing direct evidence for the normalization of tumor vascular structures regulated by IFN-γ in immunotherapy." (PMID 40370455, 2025). "Similarly, the commercially available JAK1/2 inhibitor, ruxolitinib, was previously applied to CD19 CAR-T cells against JAK-mutant B-ALL to achieve an additive effect on tumor cells and CD19-directed immunotherapy." (PMID 39891728, 2025). "We next examined the tumor-specific expression of UBA1, JAK1, and MHC-I in clinical samples." (PMID 39540840, 2025). "The utilization of PD-L1 blockers elicits the secretion of IFN-γ by CD8+T cells, leading to the inhibition of transcription and expression of SLC7A11 and SLC3A2, thereby reducing GPX4 production via the JAK1/STAT1 pathway and facilitating ferroptosis in tumor cells." (PMID 38853203, 2024). "A high level of histone lactylation in tumor-infiltrating myeloid cells induces METTL3 expression and m6A modification of Jak1 mRNA, which leads to the protein translation of Jak1 and the stimulation of downstream STAT3 signal that enhances myeloid immunosuppressive functions." (PMID 38200523, 2024). "Unlike the protective role of JAK1 in NB, we revealed that JAK1 expressed significantly higher in malignant area than in mix area or normal area, indicating its huge abundance in tumor cells at spatial dimension in most adult tumors." (PMID 39703515, 2024). "No appreciable PD-L1 expression was observed in Jak1 KO tumor cells in vivo, where blockade of unspecific binding of the staining antibody is used." (PMID 38427670, 2024). "One can speculate that the deletion of tumor B2m, LMP2, or Jak1 impacts cytokine and chemokine gradients in the TME given the altered and differential immune cell infiltration observed in these KO tumors relative to each other and to wt tumors." (PMID 38427670, 2024). "Secondly, the characteristics of JAK1 in NB have not been conclusively identified, therefore further research involving additional tumor samples, and more in vitro or in vivo experimental investigations are required to explore their biological roles within NB." (PMID 39703515, 2024). "Given the crucial involvement of JAK-STAT signaling in antigen presentation and T cell recruitment, completely inhibiting JAK1/2 activity is unlikely to enhance anti-tumor immunity or the response to ICI treatment." (PMID 38805119, 2024). "Moreover, the levels of phosphorylated JAK1/2 and STAT3 proteins were significantly lower in the tumours dissected from the shIGFBP7 group than in those from the shNC group." (PMID 39351597, 2024). "Additionally, tumor-derived miR-6794-5p was delivered to THP-1-derived macrophages and induced M2 polarization by activating the JAK1/STAT3 pathway." (PMID 38521953, 2024).